ESRP2 (epithelial splicing regulatory protein 2)
Diseases named in the same sentence as ESRP2 in open-access papers (continued):
Sharing a sentence is not in itself a finding about the gene and the disease.
tumor (continued). "Its oncogenic role depends on interacting with ESRP2 (epithelial splicing regulatory protein 2), which serves as an epithelial-specific regulatory factor in cells and may be involved in alternative mRNA splicing, which is critical for tumor progression and the epithelial–mesenchymal transition." (PMID 40362297, 2025). "To assess the in vivo tumor‐suppressive function of ESRP2, we subcutaneously injected HCC cells transfected with Vec or ESRP2, as well as shNTC or shESRP2, into the left and right dorsal flanks of nude mice." (PMID 37985644, 2024). "Downregulation of ESRP2 was frequently observed in HCC specimens and was significantly correlated with larger tumor size (Pearson χ2 test, P < 0.05) and poor differentiation status (Pearson χ2 test, P < 0.01)." (PMID 37985644, 2024). "Here, it is demonstrated that the expression of epithelial splicing regulatory protein 2 (ESRP2), an RNA splicing factor, is suppressed in fetal hepatocytes and HCC, in parallel with tumor progression." (PMID 37985644, 2024). "Interestingly, these overlapping ESRP2‐regulated splicing targets were enriched in functional clusters, such as cell cycle, cell adhesion, DNA repair, and cytoskeleton organization, indicating that they play important roles in tumor cell proliferation and migration." (PMID 37985644, 2024). "This is further supported by the correlation analysis performed in primary tumor data and by the strong ESRP1 and ESRP2 downregulation upon ERα silencing in hormone-deprived MCF-7." (PMID 35887187, 2022). "REXO2, MSI1, and ESRP2 had high expression levels in tumors compared with normal tissues, while CTU1, MAEL, and YBX2 were undetermined in both tumor and normal tissues." (PMID 33193734, 2020). "Consistent with the involvement of ESRP1 and ESRP2 in the EMT, recent studies have revealed the roles and clinical significance of these factors in tumor progression and metastasis." (PMID 28991261, 2017). "Additionally, ESRP2 expression levels were found to be positively correlated with the overall survival of HCC patients, which predicts the tumor-suppressor role of this RBP as the in the liver." (PMID 34299096, 2021). "Most of CRC cases studied (~70%) demonstrated reduced expression of both ESRP1 and ESRP2 in tumor cells compared to adjacent non-tumor tissue." (PMID 27650542, 2016). "The identified strong correlation between expression of ESRP1 and ESRP2 support the concept of a general coregulation in colon, both in tumor and non-tumor tissue cells." (PMID 27650542, 2016). "Functional assays, including foci formation, colony formation in soft agar, and transwell migration, were then performed, and the results showed that fetal TAK1 significantly rescued ESRP2‐suppressed tumor proliferation and motility, whereas adult TAK1 failed to do so." (PMID 37985644, 2024). "No significant relation with expression of ESRP2 and tumor stage was noted." (PMID 29401653, 2018). "Tumor (T) and adjacent non-tumor (N) tissue from the resection border from patients diagnosed with CRC was studied by qPCR for relative expression of ESRP1 and ESRP2." (PMID 27650542, 2016).
cancer (21 papers, 2012 to 2026). A tumor composed of atypical neoplastic, often pleomorphic cells that invade other tissues. "Expression of ESRPs was significantly linked to 11 (ESRP1)/9 (ESRP2) of 11 analyzed deletions in all cancers and to 8 (ESRP1)/9 (ESRP2) of 11 deletions in ERG-negative cancers portending a link to genomic instability." (PMID 33339518, 2020). "In contrast, careful analysis revealed a loss of ESRP1 and ESRP2 expression in cancer cells that penetrated through the basement membrane into the stroma as well as in those cells that invaded from cancer nests into stromal tissues." (PMID 32957697, 2020). "Down-regulation of ESRP1 and ESRP2 has also been closely associated with a motile phenotype of cancer cells." (PMID 27565572, 2016). "Although ESRP1 shares a similar primary structural organization with its paralog ESRP2, these two proteins have distinct functions in different cancers." (PMID 40046628, 2025). "ESRP2 was particularly attractive for further study, because of its known involvement in epithelial to mesenchymal transitions in cancer." (PMID 34520622, 2022). "In ERG-negative cancers these statistically significant associations were retained for ESRP1 in 8 and for ESRP2 in 9 chromosomal regions." (PMID 33339518, 2020). "In our study, both ESRP1 and ESRP2 were more frequently expressed in ERG-positive than in ERG-negative cancers." (PMID 33339518, 2020). "Positive nuclear ESRP1 and ESRP2 staining was more common in cancers and was recorded in 39 and 42%, respectively, of all analyzable cancers." (PMID 33339518, 2020). "For example, the fraction of tumors with detectable ESRP1 expression increased from 35.1% in ERG-negative cancers to 42.8% in ERG-positive cancers and with detectable ESRP2 expression from 36.7% in ERG-negative cancers to 51.6% in ERG-positive cancers." (PMID 33339518, 2020). "Nuclear staining for ESRP1 was seen in 38.6% (36.0% low, 2.6% high) of 12,140 interpretable cancers and in 41.9% (36.4% low, 5.3% high) of 12,962 interpretable cancers for ESRP2." (PMID 33339518, 2020). "Both ESRP1 and ESRP2 are believed to be responsible for retaining epithelial phenotypes in cancer cells and thus inhibiting EMT." (PMID 33339518, 2020). "These analyses identified ESRP1 expression, ESRP2 expression as well as our ESRP1/ESRP2 score as independent prognostic parameters in all cancers as well as the subset of ERG-negative and ERG-positive cancers in all four scenarios (p ≤ 0.05)." (PMID 33339518, 2020). "The Map3k12Δexon12 splice isoform is produced in response to ESRP2 depletion, and is usually expressed in highly metastatic cancer cell lines." (PMID 31478829, 2019). "They showed that ESRP1 overexpression enhances cancer cell proliferation and is associated with poor prognosis in BC patients, whereas ESRP2 is not." (PMID 40046628, 2025). "Therefore, we would like to focus our discussion on genes that have been reported in cancer research, such as ESRP2, MUC17, MYH10, and SSX2IP." (PMID 38893126, 2024). "While ESRP1 and ESRP2 share similar structure features and play similar roles in cancers, they may function differently." (PMID 38110955, 2023). "For ESRP2, positive nuclear staining was seen in 5393 (41.6%) of 12,962 interpretable cancers." (PMID 33339518, 2020). "The difference in the impact of Esrp2 and Esrp1 overexpression on Cdh1 levels at day 5 is consistent with a previous study demonstrating that the knockdown of Esrp paralogs has different effects on Cdh1 expression in the context of cancer cell motility." (PMID 30704403, 2019). "Epithelial splicing regulatory protein 2 (ESRP2) suppresses cancer cell motility." (PMID 28382934, 2017). "Therefore, ESRP2 methylation might act as a novel diagnosis standard for these cancer sites, thereby validating the efficacy and accuracy of our analysis methods." (PMID 32528944, 2020). "Hence, down-regulation of ESRP1 and ESRP2 in OSCC might be restricted to cells that acquire a motile phenotype during cancer invasion." (PMID 32957697, 2020).
cancer (continued). "Combined ESRPs expression analysis suggested an additive effect and showed the worst prognosis for cancers with high ESRP1 and ESRP2 expression." (PMID 33339518, 2020). "A combined staining for ESRP1 and ESRP2, was detectable in 2503 (21.6%) of 11,597 for ESRP1 and ESRP2 interpretable cancers." (PMID 33339518, 2020). "In ERG-positive cancers, a statistically significant difference was found for ESRP1 in 5 and for ESRP2 in 1 of the analyzed loci." (PMID 33339518, 2020). "A tissue microarray made from 17,747 individual cancer samples with comprehensive, pathological, clinical and molecular data was analyzed by immunohistochemistry for ESRP1 and ESRP2." (PMID 33339518, 2020). "ESRP1 and ESRP2 belong to the RNA-binding protein RBM family, also known as RBM35A and RBM35B, respectively, and are epithelial-specific splicing regulators that control the splicing process of epithelial-to-mesenchymal transition (EMT) in cancer." (PMID 36052258, 2022). "This evidence was also confirmed in MCF-7 by the analysis of copy number alterations from the Cancer Cell Lines Encyclopedia showing the amplification of ESRP1 but not of the ESRP2 gene." (PMID 35887187, 2022). "Reasons for non-informative cases (n = 5607; 31.6% for ESRP1 and n = 4785; 27.0% for ESRP2) included lack of tissue samples or absence of unequivocal cancer tissue in the TMA spot." (PMID 33339518, 2020). "Although downregulation of ESRP1 or ESRP2 expression during the EMT process has been well documented, their expression levels and the molecular mechanisms underlying their altered expression in human cancer have not been fully elucidated." (PMID 28991261, 2017). "However, it is not known whether ESRP1 and ESRP2 interact to play a role in cancer progression, and further studies are warranted to elucidate the interplay between ESRP1 and ESRP2." (PMID 38110955, 2023). "For most of 11 analyzed chromosomal regions, ESRP1 and ESRP2 expression was significantly more common in deleted than in non-deleted cancers in all analyzed cancers (11/11 for ESRP1 and 9/11 for ESRP2, p < 0.03 each, data not shown)." (PMID 33339518, 2020).
colon polyps (1 paper, 2021). "To shed more light on the mechanisms running in the background of our observation, i.e., overexpression of CD44v8-10 in colon polyps, we tested expression levels of RNA binding proteins ESRP-1 and ESRP-2 that are known to control ASP of CD44 in prostate epithelial cells." (PMID 34257584, 2021).
ESRP2 also shares sentences with these, for which no sentence is quoted: oral squamous cell carcinoma (3 papers); non‐alcoholic fatty liver disease (2); alcoholic hepatitis (1); carcinoma in situ (1); cleft palate (1); colon cancer (1); colorectal tumors (1); congenital hypopituitarism (1); gastric cancer (1); Infertility (1); lip (1); neurological disorders (1); pancreatic cancer (1); pancreatic ductal adenocarcinoma (1); renal papillary cell carcinoma (1).